ZNF37A (zinc finger protein 37A)
Description:
May be involved in transcriptional regulation.
Synonyms: KOX21; ZNF37
Tractability: PROTAC: ubiquitination databases record sites on it.
Gene: Protein-coding gene on chromosome 10 (38,094,314 to 38,150,293, forward strand). Ensembl gene ENSG00000075407.
Subcellular location: Nucleus
Subcellular location (Human Protein Atlas): Vesicles
Pathways (Reactome):
Gene expression (Transcription): Generic Transcription Pathway
Gene Ontology:
Molecular function: DNA-binding transcription factor activity; DNA-binding transcription factor activity, RNA polymerase II-specific; RNA polymerase II cis-regulatory region sequence-specific DNA binding
Biological process: regulation of DNA-templated transcription; regulation of transcription by RNA polymerase II
Cellular component: nucleus
Genetic constraint (gnomAD): Loss-of-function variants: 10 observed, 13.53 expected, observed/expected ratio (o/e) 0.74, 90% interval 0.46 to 1.25. The upper end of that interval is the gene's LOEUF score, 1.25, which puts it in group 5 of 6, group 1 being the genes least tolerant of losing a copy. Missense variants: 580 observed, 672.54 expected, observed/expected ratio (o/e) 0.86, 90% interval 0.81 to 0.92. Synonymous variants: 207 observed, 226.99 expected, observed/expected ratio (o/e) 0.91, 90% interval 0.81 to 1.02.
Homologues: Orthologues: chimpanzee ZNF37A (99% identical), macaque ZNF37A (97% identical), pig ZNF37A (79% identical). Paralogues in human: ZNF33A (51% identical), ZNF33B (50% identical), ZNF658 (48% identical), ZNF717 (48% identical), ZNF182 (46% identical), ZNF334 (46% identical), ZNF41 (45% identical), ZNF510 (45% identical), ZNF606 (45% identical), ZNF841 (45% identical), ZNF484 (44% identical), ZNF528 (44% identical), and 164 more.
Diseases named in the same sentence as ZNF37A in open-access papers:
ZNF37A is named in the same sentence as 5 diseases in open-access papers, as found by Europe PMC text mining. Sharing a sentence is not in itself a finding about the gene and the disease. The quoted sentences say what the papers report.
colorectal cancer (1 paper, 2024). A primary or metastatic malignant neoplasm that affects the colon or rectum. "For instance, ZNF37A has been found to be involved in promoting tumor metastasis via the THSD4/TGF-β axis in colorectal cancer." (PMID 39273015, 2024).
myotonic dystrophy (1 paper, 2025). An inherited progressive disorder affecting the muscles. "Finally, ZNF37A, previously implicated in myotonic dystrophy, was the most enriched TFBS in DMRs, distinguishing A-RRMS from S-RRMS." (PMID 40034794, 2025).
tumor (2 papers, 2023 to 2024). "Interestingly, the enhancement of TGF-β signaling by ZNF37A-induced repression of the tumor microenvironment regulator THSD4 stimulates cytokine generation by cancer-associated fibroblasts to promote tumor spread." (PMID 37373394, 2023).
cancer (1 paper, 2024). A tumor composed of atypical neoplastic, often pleomorphic cells that invade other tissues. "We identified several TFs, including GTF2I, NFIB, NFATC4, ZNF37A, KLF13, and ZNF507, involved in cancer metastasis." (PMID 39273015, 2024).
ZNF37A also shares sentences with these, for which no sentence is quoted: genetic diseases (1 paper).